S100A4 (S100 calcium binding protein A4)
Diseases named in the same sentence as S100A4 in open-access papers (continued):
Sharing a sentence is not in itself a finding about the gene and the disease.
gastric cancer (continued). "Further in vivo and in vitro experiments confirmed that OSTM1 promotes the proliferation, migration, and invasion abilities of gastric-cancer cells by enhancing the expression and activity of S100A4." (PMID 39852172, 2025). "Even though we successfully block CLDN18.2, the effects present between tumor cells and CAFs, particularly the promotion of gastric cancer metastasis by the secretion of S100A4, remain intact." (PMID 38200591, 2024). "Using Western blotting and quantitative PCR, we found that the expression levels of FAP, α-SMA, and S100A4 were significantly higher in CAFs compared to NAFs, confirming the successful extraction of primary CAFs from gastric cancer patients." (PMID 38200591, 2024). "Yet, S100A4 expression in gastric cancer has been analyzed exclusively in studies with patient cohorts of Asian origin." (PMID 35326507, 2022). "The possibility of detecting S100A4 in gastric cancer patients’ blood plasma makes this marker also interesting as a follow-up parameter." (PMID 35326507, 2022). "Hypoxic regulation of S100A4 was demonstrated in BGC823 gastric cancer cells where exposure to hypoxic conditions resulted in higher transcript levels of S100A4 as compared to normoxic conditions." (PMID 34360919, 2021). "RPS12 gene closely associates with gastric cancer cell-proliferation and migration and the inhibition of RPS12 expression using RNAi has been found to reduce S100A4 expression and decrease S100A4 promoter activity in gastric cancer cells." (PMID 29069865, 2017). "One of the four mAbs, namely 2A12D10B2, recognized human S100A4 as indicated by immunohistochemical staining of human gastric carcinoma specimens and recombinant S100A4 was functionally expressed in E. coli." (PMID 25339497, 2015). "Immunohistochemical analysis revealed that the mAbs were suitable for detecting S100A4 expression in human gastric carcinoma specimens." (PMID 25339497, 2015). "Consistent with the results from previous reports, our data confirmed that S100A4 plays a critical role in the cell migration of gastric cancer cell lines." (PMID 25310523, 2014). "In the present study, we used gastric cancer cell lines as a model to investigate the involvement of S100A4 in drug responsiveness." (PMID 25310523, 2014). "Despite these previous findings, however, the involvement of S100A4 in the drug responsiveness of gastric cancer remains less well understood." (PMID 25310523, 2014). "To further explore the potential role of S100A4 in the drug resistance of gastric cancers, we herein investigated the correlation of S100A4 expression levels with the survival of gastric cancer cell lines exposed to anticancer drug treatment." (PMID 25310523, 2014). "This suggests that OSTM1 may positively regulate S100A4 expression, and the two may play a synergistic role in the metastasis of gastric cancer." (PMID 39852172, 2025). "This suggests that S100A4 mediates the role of OSTM1 in promoting gastric-cancer lung metastasis." (PMID 39852172, 2025). "These in vivo experimental results support the inference that OSTM1 positively regulates S100A4 expression, which may affect gastric-cancer lung metastasis." (PMID 39852172, 2025). "Additionally, this study examines potential therapeutic strategies targeting the OSTM1/S100A4 signaling pathway, providing new insights and approaches for the treatment of gastric cancer." (PMID 39852172, 2025). "Although existing research has revealed the potential roles of OSTM1 and S100A4 in tumor development, their specific interactions and mechanisms in gastric cancer remain unclear." (PMID 39852172, 2025). "This indicates that high expression of S100A4 may be an indicator of poor prognosis in gastric-cancer patients, suggesting that S100A4 may promote the progression of gastric cancer." (PMID 39852172, 2025).
gastric cancer (continued). "Furthermore, we employed siRNA-mediated suppression to effectively attenuate the expression of S100A4 in CAFs, thus assessing its implications for the migratory dynamics of gastric cancer cells." (PMID 38200591, 2024). "Five gastric cancer cell lines were assessed for S100A4 expression." (PMID 35326507, 2022). "Moreover, we have also observed upregulation of S100A4 transcripts in plasma from patients with CRC or gastric cancer." (PMID 30927479, 2019). "We speculated that S100A4 might regulate miR-3189-3p to affect its function in gastric cancer cells." (PMID 29342841, 2018). "Besides, mRNA and protein levels of S100A4 have been found to be upregulated in gastric cancer cells after being exposed to hypoxia or hypoxia mimicking cobalt chloride treatments." (PMID 29069865, 2017). "S100A4 oxidation could be induced by hydrogen peroxide treatment in gastric cancer cells, decreasing S100A4-PP5 interaction and the inhibition of PP5 activation process, which is closely associated with gastric cancer cell malignant phenotypes." (PMID 29069865, 2017). "Increasing S100A4 expression is closely correlated to breast, colorectal and gastric carcinomas." (PMID 25339497, 2015). "Here, we report that S100A4 appears to have little effect on drug responsiveness in various gastric cancer cell lines, suggesting that we should identify other relevant factors in order to improve our therapeutic strategies against gastric cancer." (PMID 25310523, 2014). "Considering the upregulation of S100A4 in metastatic tumors and the literature correlating its expression with poor prognosis, we investigated whether S100A4 may mediate chemotherapeutic resistance in gastric cancer." (PMID 25310523, 2014). "Clinical studies have convincingly demonstrated that significant expression of S100A4 in primary tumors is indicative of poor prognosis, and that S100A4 may be a useful marker for predicting the development, progression and metastasis of human gastric cancer." (PMID 25310523, 2014). "First, we examined the expression levels of S100A4 in seven gastric cancer cell lines." (PMID 25310523, 2014). "The increased expression of S100A4 is correlated with breast, colorectal and gastric carcinoma, and it has been suggested that S100A4 may be used in the early diagnosis and prognosis of cancer as a complementary specific biomarker." (PMID 24944689, 2014). "The expression of S100A4 is significantly increased in several tumors, including gastric cancers." (PMID 24216696, 2013). "Further studies are needed to determine whether NRP-2 mediates prosurvival functions in gastric cancer cells via S100A4." (PMID 22028766, 2011). "Moreover, S100A4 expression has been detected in patients that had received adjuvant 5-fluorouracil, and has been proposed to be a predictive factor of relapse in gastric cancer." (PMID 20515499, 2010). "In summary, this study systematically confirms that OSTM1 may play an important role in the progression and metastasis of gastric cancer by positively regulating S100A4 expression from multiple levels, including gastric-cancer patient samples, in vitro cells, and animal models." (PMID 39852172, 2025). "Furthermore, we also explored the role of OSTM1 and S100A4 in the gastric-cancer microenvironment." (PMID 39852172, 2025). "Firstly, although we have preliminarily revealed the important role of the OSTM1–S100A4 axis in gastric-cancer progression, the deeper molecular mechanisms of how OSTM1 regulates S100A4 expression remain unclear, requiring further mechanistic studies for elucidation." (PMID 39852172, 2025).
gastric cancer (continued). "By investigating the roles of OSTM1 and S100A4 in gastric cancer, this study not only aids in understanding the molecular pathophysiology of gastric cancer but may also offer new molecular targets for targeted therapy, holding significant scientific value and clinical implications." (PMID 39852172, 2025). "Thus, we established for the first time a non-invasive, plasma-based assay for the quantification of circulating S100A4 transcripts in blood of colon, rectal, and gastric cancer patients, that allows clinical application routinely for diagnosis, prognosis and for monitoring treatment success." (PMID 27331819, 2016). "We determined increased S100A4 transcripts in cancer patients of each entity and all disease stages, compared with tumor-free volunteers, with sensitivities of 96%, 74%, and 90% and specificities of 59%, 82%, and 71%, for colon, rectal, and gastric cancer patients, respectively." (PMID 27331819, 2016). "Therefore, we tested whether RPN2 depletion could have a synergistic effect in S100A4-knockdown gastric cancer cells." (PMID 25310523, 2014). "Our present results suggest that in spite of S100A4, the acquisition of cell survival and growth ability in response to chemotherapy may result from the integration of other factors, at least among the tested gastric cancer cell lines." (PMID 25310523, 2014). "The aim of this study was to determine the correlation of S100A4 expression with the progression, prognosis and clinical pathology of gastric cancer (GC) in young pateints." (PMID 23760193, 2013). "Based on phenotypic, omics and molecular evidences, we proved that a characteristic marker of CAFs, S100A4, interacts with CLDN18.2 to accelerate the metastatic progression of gastric cancer in a CAF-dependent manner." (PMID 38200591, 2024). "S100A4 serves as one of the most important markers of CAFs, existing literature reports suggest that S100A4 activates the TGF-β pathway, promoting the epithelial-mesenchymal transition of gastric cancer cells, and ultimately contributing to distant metastasis." (PMID 38200591, 2024). "By analyzing the DNA methylation data of TCGA gastric cancer database, there were 12 DNA methylation sites in VIM, 8 in CDH1, 3 in S100A4, 7 in EPCAM, and 6 in VCL." (PMID 33535187, 2021). "In order to clarify the role of EMT and distant metastasis, we first analyzed the mRNA expression of VIM, CDH1, S100A4 and EPCAM in human gastric cancer samples from the Cancer Genome Atlas (TCGA) data." (PMID 33535187, 2021). "When combining S100A4 with circulating transcripts of MACC1, improved survival prediction was seen for newly diagnosed CRC as well as gastric cancer patients." (PMID 27331819, 2016). "However, the involvement of S100A4 in the drug responsiveness of gastric cancer remains unclear." (PMID 25310523, 2014). "Among them, four genes, including S100A2, S100A4, S100A7 and S100A10, were reported to overexpressed in gastric cancer previously." (PMID 18793447, 2008). "In other studies, an inverse correlation between S100A4 and members of the E-cadherin–catenin complex was revealed in non small cell lung cancer (NSCLC) and gastric cancer." (PMID 12439718, 2002). "In gastric-cancer cell models, cells overexpressing OSTM1 exhibited higher invasive and migratory capabilities, while these effects were significantly attenuated after S100A4 knockdown." (PMID 39852172, 2025). "S100A4, as a key factor promoting tumor invasion and metastasis, is regulated by OSTM1, providing new clues and potential therapeutic targets for elucidating the mechanism of gastric-cancer metastasis." (PMID 39852172, 2025). "In addition, S100A4 interacts with MYH9 to promote the migration and invasion of gastric cancer cells via TGF-β-mediated EMT." (PMID 37875476, 2023). "There are several studies that found a link between S100A4 expression, lymph node metastasis and prognosis, but a meta-analysis of seven gastric cancer studies did not recapitulate that correlation." (PMID 35326507, 2022).
gastric cancer (continued). "In addition, we demonstrated that HIF-1α can specifically activate transcription of an S100A4 promoter through the HIF-1α binding site, probably located at − 1838 to − 1829; this is in contrast to earlier study that used a gastric carcinoma cell line." (PMID 35392912, 2022). "Among them, S100A4 and S100A6 have been reported to be epigenetically up-regulated in nasopharyngeal and gastric cancer by DNA hypomethylation over their gene promoter regions, while S100A2 and S100A10 down-regulated in head/neck and pituitary cancer by DNA hypermethylation." (PMID 28498804, 2017). "Thus we combined detection of circulating transcripts of S100A4 with those of the MACC1 gene for CRC and gastric cancer patients." (PMID 27331819, 2016). "We found that siRNA-mediated knockdown of S100A4 in gastric cancer cell lines significantly reduced cell migration but did not alter cell viability following administration of the tested drugs." (PMID 25310523, 2014). "Here, we reported that ectopic expression of S100A4 did not promote anticancer drug resistance in gastric cancer cells, and S100A4 knockdown had little effect on the survival of drug-treated cells." (PMID 25310523, 2014). "In addition, molecular analysis has revealed that several S100s, including S100A2, S100A4, S100A7 and S100A10, exhibit altered expression levels in gastric cancer." (PMID 18793447, 2008). "S100A4, a member of the S100 family of Ca2+-binding proteins, is known to be involved in cancer cell motility by its ability to activate non-muscle myosin, and has been shown to be related to gastric cancer progression." (PMID 25079072, 2014). "In order to better identify gastric cancer patients with EMT, EMT and non-EMT patients were distinguished by combining the expression levels of VIM (high expression), CDH1 (low expression), S100A4 (high expression) and EPCAM (low expression)." (PMID 33535187, 2021). "S100A4, S100A6 and S100A7 were shown to be upregulated in gastric cancer in only one dataset but did not exist in the other two datasets." (PMID 18793447, 2008).
pulmonary fibrosis (35 papers, 2012 to 2026). Chronic progressive interstitial lung disorder characterized by the replacement of the lung tissue by connective tissue, leading to progressive dyspnea, respiratory failure, or right heart failure. "S100A4 loss protects from experimental in vivo pulmonary fibrosis, and S100A4 expression is dysregulated in human IPF fibroblasts." (PMID 38072048, 2024). "The purpose of this research was to evaluate the associations among S100A4, S1P, and pulmonary fibrosis in COPD patients based on a case-control study." (PMID 35165531, 2022). "Up to now, S100A4 has been implicated in the development of many organ fibrosis, such as kidney fibrosis, liver fibrosis, pulmonary fibrosis and artery diseases, cardiac hypertrophy and fibrosis and rheumatoid arthritis." (PMID 32307910, 2020). "This was proven by the findings that S100A4 deficiency in vivo attenuated lung fibrosis and neutralizing exogenous S100A4 by anti-S100A4 has the potential to prevent the fibrosis." (PMID 30127784, 2018). "Taken together, S100A4 released by macrophages promotes pulmonary fibrosis through activation of lung fibroblasts which is associated with S1P." (PMID 30127784, 2018). "Proving the causal connection, adoptive transfer of S100A4+ macrophages to bleomycin-treated syngeneic S100A4−/− mice augmented pulmonary fibrosis." (PMID 30127784, 2018). "Furthermore, S100A4 loss protects against murine in vivo pulmonary fibrosis, and S100A4 expression is dysregulated in IPF." (PMID 38072048, 2024). "In addition to pulmonary fibrosis, S100A4 has been implicated in fibrosis in the liver, heart, skin, and kidney." (PMID 38072048, 2024). "Though it may seem counterintuitive that an ECM-degrading fibroblast is implicated in fibrotic injury, S100A4 is similarly overexpressed in lung tissue of idiopathic pulmonary fibrosis patients as well as in cardiac hypertrophy and kidney fibrosis." (PMID 37090702, 2023). "Interestingly, S100A4 has further been implicated in PH development and RVH, and increased S100A4 levels have been reported in the crosstalk between macrophages and pulmonary fibroblasts to promote pulmonary fibrosis." (PMID 35053115, 2022). "Consistent with this, S100a4 -/- mice are protected from lung fibrosis, including in a bleomycin-induced lung fibrosis model." (PMID 40078995, 2025). "Using additional robust, quantitative, physiologic, and clinically relevant readouts, our work confirms and extends prior work showing that global KO or pharmacologic inhibition of S100A4 protects against bleomycin-induced pulmonary fibrosis in mice." (PMID 38072048, 2024). "S100A4 has been widely used as a marker of lung fibroblast identification in experimental studies, such as in bleomycin-induced lung fibrosis animal models." (PMID 37893169, 2023). "Expression of S100A4 was significantly increased in a dose‐ and time‐dependent manner in lung tissues of bleomycin‐induced murine models for pulmonary fibrosis and localized mainly in lung fibroblasts." (PMID 37873538, 2023). "Precedent for the clinical application of secreted S100A4, this protein has also been reported to be elevated in the bronchoalveolar fluid of patients with idiopathic pulmonary fibrosis and in the blood of patients with rheumatoid arthritis." (PMID 37090702, 2023). "The results presented in this study show that JWH133 exerts a protective effect against pulmonary fibrosis by inhibiting the FAK/ERK/S100A4 pathway.Therefore, JWH133 holds promise as a potential therapeutic target for pulmonary fibrosis." (PMID 37957604, 2023). "In this study, an obvious elevation in S100A4 level was found in mice with BLM-induced pulmonary fibrosis." (PMID 37957604, 2023). "In summary, JWH133 ameliorates the symptoms of pulmonary fibrosis in mice through the FAK/ERK/S100A4 pathway." (PMID 37957604, 2023).